MTARC2 (mitochondrial amidoxime reducing component 2)
Description:
Catalyzes the reduction of N-oxygenated molecules, acting as a counterpart of cytochrome P450 and flavin-containing monooxygenases in metabolic cycles. As a component of prodrug-converting system, reduces a multitude of N-hydroxylated prodrugs particularly amidoximes, leading to increased drug bioavailability. May be involved in mitochondrial N(omega)-hydroxy-L-arginine (NOHA) reduction, regulating endogenous nitric oxide levels and biosynthesis. Postulated to cleave the N-OH bond of N-hydroxylated substrates in concert with electron transfer from NADH to cytochrome b5 reductase then to cytochrome b5, the ultimate electron donor that primes the active site for substrate reduction.
Synonyms: mARC2; MOSC2; FLJ20605
Tractability: Antibody: UniProt places it where antibodies can reach, with medium confidence. PROTAC: UniProt records ubiquitination sites on it; ubiquitination databases record sites on it.
Target class: Enzyme; Oxidoreductase
Gene: Protein-coding gene on chromosome 1 (220,748,122 to 220,784,824, forward strand). Ensembl gene ENSG00000117791.
Subcellular location: Mitochondrion outer membrane; Peroxisome
Pathways (Reactome):
Metabolism: Phase I - Functionalization of compounds
Gene Ontology:
Molecular function: molybdenum ion binding; molybdopterin cofactor binding; nitrate reductase activity; nitrite reductase activity; oxidoreductase activity, acting on other nitrogenous compounds as donors; catalytic activity; pyridoxal phosphate binding
Biological process: cellular detoxification of nitrogen compound; nitrate metabolic process; nitric oxide biosynthetic process; detoxification of nitrogen compound
Cellular component: mitochondrion; mitochondrial outer membrane; peroxisome
Genetic constraint (gnomAD): Loss-of-function variants: 27 observed, 32.13 expected, observed/expected ratio (o/e) 0.84, 90% interval 0.62 to 1.16. The upper end of that interval is the gene's LOEUF score, 1.16, which puts it in group 5 of 6, group 1 being the genes least tolerant of losing a copy. Missense variants: 397 observed, 382.94 expected, observed/expected ratio (o/e) 1.04, 90% interval 0.95 to 1.13. Synonymous variants: 150 observed, 141.01 expected, observed/expected ratio (o/e) 1.06, 90% interval 0.93 to 1.22.
Homologues: Orthologues: chimpanzee MTARC2 (99% identical), macaque MTARC2 (95% identical), mouse Mtarc2 (75% identical), rat Mtarc2 (74% identical), guinea pig MTARC2 (72% identical), pig MTARC2 (71% identical), Caenorhabditis elegans F22B8.7 (31% identical), Caenorhabditis elegans F53E10.1 (30% identical). Paralogues in human: MTARC1 (65% identical), MOCOS (26% identical).
Diseases named in the same sentence as MTARC2 in open-access papers:
MTARC2 is named in the same sentence as 18 diseases in open-access papers, as found by Europe PMC text mining. Sharing a sentence is not in itself a finding about the gene and the disease. The quoted sentences say what the papers report.
Obesity (5 papers, 2014 to 2025). Accumulation of substantial excess body fat. "MARC2 (mitochondrial amidoxime reducing component 2) plays an important role in obesity by enhancing lipid synthesis." (PMID 32331484, 2020).
hepatocellular carcinoma (2 papers, 2021 to 2022). A malignant tumor that arises from hepatocytes. "MTARC2, which shares a high degree of sequence similarity with MTARC1, was downregulated in human hepatocellular cancer tissues and cells." (PMID 36106120, 2022).
liver steatosis (1 paper, 2025). "Grade 1 liver steatosis was found in all seven Mtarc2-KO females and five out of the eight C57BL/6 N females fed the WD." (PMID 40437401, 2025).
steatosis (1 paper, 2025). Increased lipid within the cytoplasm of cells. "However, although we confirmed our previous findings, which showed significantly lower body weight gain and total fat in Mtarc2-KO mice than in wild-type mice, liver accumulation of FAs and steatosis grade depended much less on the strain or sex of mice than other measures." (PMID 40437401, 2025). "Steatosis reached grade 3 in eight out of 10 C57BL/6 N males and only two out of 10 Mtarc2-KO males fed the WD." (PMID 40437401, 2025).
infection (1 paper, 2025). The state of being infected such as from the introduction of a foreign agent such as serum, vaccine, antigenic substance or organism. "Similarly, mitochondrial amidoxime reducing component 2 (MTARC2) was highlighted in the rules on the LightGBM feature list, showing elevated expression at the early challenge stage of infection." (PMID 40724541, 2025).
MTARC2 also shares sentences with these, for which no sentence is quoted: cancer (4 papers); tumor (2); adenocarcinoma (1); adenoma (1); clear cell renal cell carcinoma (1); colon cancer (1); liver disease (1); metabolic disease (1); multiple myeloma (1); myeloid neoplasm (1); prostate carcinoma (1); renal cell carcinoma (1); schizophrenia (1).